NDC80 (NDC80 kinetochore complex component)
Diseases named in the same sentence as NDC80 in open-access papers (continued):
Sharing a sentence is not in itself a finding about the gene and the disease.
cancer (continued). "Using the TCGA/TARGET/GTEx RNA-seq data-set which contains data from 23 cancer types and corresponding normal tissues, we analyzed the mRNA expression profile of NDC80 complex components in normal and tumor tissues." (PMID 39513104, 2024). "Recent evidence suggests that the NDC80 complex components are significantly overexpressed and play significant roles in a variety of cancers." (PMID 39513104, 2024). "We compared the expression levels of NDC80 complex components in different tumor stages in pan-cancer." (PMID 39513104, 2024). "The results showed a significant positive correlation between immune checkpoint genes and NDC80 complex components across various cancer types, including BRCA, BLCA, KIRC, LIHC, LUAD, and THCA." (PMID 39513104, 2024). "We then used DAVID to identify the GO functional enrichment and KEGG pathway among the NDC80 complex components related genes in pan-cancer." (PMID 39513104, 2024). "The results indicated that patients with high expression of NDC80 complex components had higher expression levels of immune checkpoints in certain cancer types, such as BLCA, BRCA, and LIHC." (PMID 39513104, 2024). "Next, we corroborated the expression patterns of NDC80 complex components in 33 cancer types using the TCGA and GTEx data." (PMID 39513104, 2024). "Meanwhile, we found that the expression levels of NDC80 complex components were positively correlated with tumor staging in various cancer types, which verified the crucial role of NDC80 complex components in tumor progression." (PMID 39513104, 2024). "Herein, we assessed the expression and prognostic value of NDC80 complex components in pan-cancer and interrogated their potential functions in tumor context through multiple databases and software." (PMID 39513104, 2024). "Particularly noteworthy was the finding that the expression of the NDC80 complex components showed a significant and positive correlation with Th2 cell in almost all TCGA cancer types." (PMID 39513104, 2024). "To further investigate the potential function of NDC80 complex components in tumor context, we preformed the functional state of NDC80 complex components in various cancer types through CancerSEA at the single-cell level." (PMID 39513104, 2024). "Our results revealed a strong and significant correlation between the expression of NDC80 complex components and immune cell infiltration across different TCGA cancer types." (PMID 39513104, 2024). "Our results were consistent with previous studies on the prognosis of NDC80 complex components in certain cancer types and demonstrated that NDC80 complex components were promising prognostic biomarkers in pan-cancer." (PMID 39513104, 2024). "Next, we thoroughly analyzed the correlation between the expression of NDC80 complex components and the infiltration of 64 immune cells in pan-cancer based on the xCell algorithm." (PMID 39513104, 2024). "Hec1 is a component of the Ndc80 kinetochore complex and is frequently upregulated in various cancers." (PMID 39544289, 2024). "Of the other two genes, NDC80 (previously known as Hec1) is a key regulator of G2/M phase and is often overexpressed in human cancers, including MM." (PMID 37696786, 2023). "Although NUF2 (Ndc80 kinetochore complex component) has been suggested to play an important role in the development of many cancers, but little is known about its function and the roles of proteins that regulate NUF2 in OC." (PMID 36670423, 2023). "Strikingly, it was reported that the human Ndc80 subunit (also known as “highly expressed in cancer 1” HEC1) can fully complement its ortholog in S. cerevisiae, despite a <30% amino acid (aa) sequence identity." (PMID 37962556, 2023). "The combined results of pan-cancer analyses showed that the expression of NDC80 was notably elevated in LUAD and LUSC samples." (PMID 36105209, 2022). "Meanwhile, the NDC80 expression level was significantly increased in 9 kinds of cancers from CPTAC datasets." (PMID 36105209, 2022).
cancer (continued). "The results obtained using TCGA datasets showed that transcriptional expression levels of NDC80 were higher in 19 types of cancers, as compared to those for matched normal samples." (PMID 36105209, 2022). "The seven DEGs (AURKA, BUB1, CDC6, MAD2L1, NDC80, ZWINT, and TIMELESS) coexpressed only in the LC&OC coexpression network have been associated with the acquisition of the hallmarks of cancer." (PMID 36101460, 2022). "The overexpression of NDC80 has been identified to be an oncogenic biomarker with poor prognosis in several cancers, including gastric and ovarian cancer, and osteosarcoma." (PMID 36105209, 2022). "NDC80 Kinetochore complex was previously reported to be involved in various types of cancers, including prostate and breast cancer." (PMID 34728699, 2021). "High NDC80 levels were found in cancers, and overexpression of NDC80 in mice led to abnormal spindle formation, hyperactivation of the mitotic checkpoint and initiation of the tumorigenic events." (PMID 34207779, 2021). "Recent studies have reported that the aberrant expression of Ndc80 complex is involved in the progression of human cancer." (PMID 32742802, 2020). "The related mechanism investigation suggested inactivation of pRb signaling pathway increases NDC80 expression and leads to the uncontrolled cell cycle progression of cancer cells." (PMID 29341479, 2018). "The mRNA and protein levels of NDC80 (also called HEC1), a member of the NDC80 complex, are commonly overexpressed in several human cancers including GC." (PMID 30065754, 2018). "We show that Bod1 kinetochore targeting depends on the outer kinetochore protein Ndc80 (Nuclear division cycle protein 80, also known as highly expressed in cancer protein Hec1)." (PMID 29142109, 2017). "NDC80, a kinetochore outer layer component and spindle checkpoint regulator, is highly expressed in a variety of human cancers." (PMID 29246203, 2017). "NDC80, also called as Hec1 (highly expressed in cancer 1), is involved in the organization and stabilization of microtubule-kinetochore interactions and is required for proper chromosome segregation." (PMID 26468983, 2015). "HEC1, a Ndc80 complex protein localized at kinetochores and highly expressed in cancer, is phosphorylated by NEK2A at 165-serine." (PMID 25705694, 2015). "Identification of the Ndc80 internal loop as a protein-protein interaction motif has shed light on our understanding of Ndc80 overexpression and cancer formation." (PMID 25557589, 2015). "HEC1 (Highly expressed in Cancer) is a component of the Ndc80/HEC1 complex required for kinetochore microtubule attachment to the kinetochore." (PMID 23946484, 2013). "We analysed cdc14A, that regulates centrosome separation and activates the anaphase promoting complex cdh1/APC, Ndc80/Hec1 (Highly Expressed in Cancer;) a component of APC and Aurora Kinase B, a key regulator of chromosome segregation." (PMID 21187932, 2010). "Targeting SPC25 could therefore offer a more specific approach to modulating mitotic functions compared to other NDC80 components, making it a promising candidate for therapeutic intervention in cancer treatment." (PMID 40400636, 2025). "We also examined the prognostic value of NDC80 complex components by performing the Kaplan-Meier survival curve in pan-cancer samples and found that high expression of NDC80 complex components was a risk factor and associated with poor prognosis as indicated by OS, DSS, DFI, and PFI." (PMID 39513104, 2024).
cancer (continued). "Our study also lacks experimental evidence on whether the influence of NDC80 complex components on tumor cell growth is universal in pan-cancer and the specific molecular mechanisms by which NDC80 complex components regulate tumor cell growth." (PMID 39513104, 2024). "Interestingly, only a few cancer types demonstrated lower expression of NDC80 complex components in tumor tissues." (PMID 39513104, 2024). "Our findings provide novel insights into the effect of NDC80 on radioresistance in cancer cells, and suggest that NDC80 could serve as a drug target for improving radiosensitivity." (PMID 36105209, 2022). "With regard to cancer treatment, NDC80 might become a novel target for increasing the sensitivity of pemigatinib used for the treatment of cholangiocarcinoma." (PMID 36105209, 2022). "And NDC80 was notably enriched in cell cycle, covering overall mitotic phase at the metaphase, anaphase, and prometaphase transition, with impairment function of mitotic spindle checkpoint found in many types of cancer." (PMID 33493131, 2021). "This cytogenetic location belongs to genes such as NDC80, known to be highly expressed in cancer." (PMID 34063545, 2021). "However, as is the compound will provide a useful experimental tool to inhibit Ndc80 complex function for cell and cancer biologists who are investigating mitotic processes." (PMID 34926718, 2021). "Because of the important roles of the Ndc80 complex in mitosis and the overexpression of Hec1 in human tumors, targeting the complex may possess therapeutic value in the treatment of cancer." (PMID 34926718, 2021). "Although the agents targeting the components of kinetochore complex including Ndc80 and Nuf2 have been shown to have anti-cancer effects, this is the first report, to the best of our knowledge, to show the mechanism to suppress cancer cell proliferation through the degradation of Mis12." (PMID 31222108, 2019). "NDC80 (Nuclear division cycle 80) is also known as highly expressed in cancer 1 (HEC1)." (PMID 31788359, 2019). "Taken together, these evidences collectively suggest that NDC80 may be a promising molecular biomarker for cancer diagnosis and treatment." (PMID 29341479, 2018). "have proved NDC80 overexpression is correlated with advanced tumor stage in pancreatic cancer patients, and its downregulation inhibits the proliferative and antiapoptotic ability of cancer cells." (PMID 29341479, 2018). "Increased Ndc80 levels, as reported in cancer, may compromise error correction if they lead to increased microtubule attachments, contributing to the increased aneuploidy observed." (PMID 28939613, 2017). "Interestingly, the expression of Ndc80/Hec1-associated genes (i.e. Nuf2, Spc24, Spc25 and Nek2) is coordinately up-regulated in Ndc80/Hec1-overexpressed cancer cells." (PMID 25557589, 2015). "Despite this, whether these genes/proteins are coordinately up-regulated with Ndc80 in cancer cells remains to be examined." (PMID 25557589, 2015). "Interestingly, some SRSF1 translational targets, including NDC80 and centrosomal proteins, have been previously identified in an siRNA screen looking for proteins involved in centrosome clustering in cancer cells." (PMID 24842991, 2014). "The Kaplan-Meier curve and log-rank test analysis revealed that increased NDC80, NUF2, SPC24, and SPC25 mRNA levels were all significantly associated with the overall survival (OS), disease-free survival (DFS), disease-free interval (DFI), and progression-free interval (PFI) of pan-cancer samples." (PMID 39513104, 2024).
cancer (continued). "NUF2 component of NDC80 kinetochore complex (NUF2) is a component of a conserved protein complex associated with the centromere, and one study had demonstrated that NUF2 upregulation is a common feature of many cancers (TCGA-SARC dataset was also incorporated in this study)." (PMID 35126643, 2022). "Toward this, we performed intersection analysis on the top 200 genes having highest correlation with NDC80 complex components - NDC80, NUFS, SPC24, and SPC25 respectively at the pan-cancer level, and identified 109 overlapping genes." (PMID 39513104, 2024). "It was found that POLE2, GABARAPL1, PIK3R1, NDC80, and TPX2 play critical roles in the response and overall survival in cancer patients under PD-L1 inhibitor treatment." (PMID 37240068, 2023). "In our research, NDC80, NPAS2, and AHNAK2 were sifted out from the ISGs family to develop a signature that improved the prediction of OS for pan-cancer patients." (PMID 35813478, 2022). "The Ndc80 kinetochore complex component (NUF2) is involved in the development and progression of several cancers." (PMID 35813477, 2022). "NDC80 kinetochore complex component (NUF2) is upregulated and plays an important role in various human cancers." (PMID 36620547, 2022). "The super-associations of protein interactions such as complexes and clusters revealed proteins from the NDC80 kinetochore complex, MCM complex, centromere complex and spliceosome complex as important interactors mediating cancer progression." (PMID 34728699, 2021). "Studies have confirmed that NDC80 and CEP250, in connection with NEK2, participated in the mechanism of some cancers." (PMID 33109182, 2020). "Intriguingly, several of the Ndc80 internal loop interactors, such as the Ska complex, TACC-TOG complex and kinesin-8, are also up-regulated in several cancers." (PMID 25557589, 2015). "Recent advancements in drug development against the Ndc80/Hec1 and TACC proteins seem promising for clinical use in cancer treatment." (PMID 25557589, 2015). "Due to their roles in controlling mitotic progression and chromosome segregation, both Ndc80/Hec1 and TACC proteins are considered potential targets for cancer drug development." (PMID 25557589, 2015). "Hec1 (NDC80) is an integral part of the kinetochore and is overexpressed in a variety of human cancers, making it an attractive molecular target for the design of novel anticancer therapeutics." (PMID 24401611, 2014). "The cancer patients with higher expression of NDC80, NUF2, SPC24, and SPC25 were predicted to have worse OS, DFS, DFI, and PFI, which suggested that NDC80 complex components may be potential prognostic indicator molecules in pan-cancer." (PMID 39513104, 2024). "Furthermore, the immunohistochemical staining results based on the HPA database revealed a significantly high positivity of the ZWINT, RRM2, NDC80, KIF4A, CEP55, CENPU, and CENPF genes in cancer tissues compared to adjacent normal tissues." (PMID 35028418, 2022). "Chromosome oscillations are attenuated in cancer cell lines and in cells with non-phosphorylatable Ndc80 or deletions of the outer kinetochore protein Dam1; all of these situations yield errors in attachment correction." (PMID 34445523, 2021). "NDC80 could also be a promising marker to identify ACC and estimate the prognosis of this cancer." (PMID 35983531, 2022). "The crucial role of the Ndc80 complex in mediating a key function for chromosome segregation in mitosis and the recurrent HEC1 up-regulation in different human cancers suggest that HEC1 deregulation may be an important step in the multistage process of cancer." (PMID 21297979, 2011).
tumor (49 papers, 2005 to 2025). "As expected, an increasing level of AURKA and NDC80 as well as Ki-67 protein was associated with increasing tumor grades." (PMID 26468983, 2015). "Ndc80 depletion by RNAi has been shown to cause mitotic delay, persistent activation of the spindle checkpoint and subsequent cell death, and in nude mouse xenografts, suppression of tumor growth." (PMID 34926718, 2021). "Next, we investigated the association alterations of NDC80 complex components to 109 overlapping genes between normal and tumor tissues, and we observed that 44 of 109 overlapping genes had a higher association with NDC80 complex components in the tumor context compared with normal tissues." (PMID 39513104, 2024). "Both heterozygous and homozygous CNV analyses showed significant amplification for DCAF13 and FAM83D and deletion for FUCA2, UQCRH, and NDC80 in tumor samples." (PMID 41355397, 2025). "We begin by exploring the structural and functional characteristics of SPC25 within the NDC80 complex, followed by its dysregulation in different tumor types and its impact on tumor progression." (PMID 40400636, 2025). "Spindle component 25 (SPC25) is a key component of the nuclear division cycle 80 (NDC80) complex, and its high expression promotes tumor cell proliferation by inducing mitotic disorder." (PMID 40454580, 2025). "We further examined the association alterations between the 109 overlapping genes and the NDC80 complex components in the normal tissues and tumor tissues." (PMID 39513104, 2024). "Further, functional enrichment analysis of NDC80 complex components related genes in the tumor context was performed." (PMID 39513104, 2024). "Some previous studies have linked the NDC80 kinetochore complex component HEC1 to immune cell infiltration and tumor‐specific epitopes." (PMID 39021287, 2024). "We also discovered that NDC80 complex components play pivotal roles in cell division, and the cell cycle within the tumor context." (PMID 39513104, 2024). "For tumor stage, significant differences among stage 1, stage 2, and stage 3 were shown in NDC80, CCNB1, KIF20A, DTL, and TOP2A of the key genes from Jia Liver data set (P < 0.05)." (PMID 34746301, 2021). "In univariate Cox regression analysis, HCC recurrence, pathologic stage, tumor size, and NEK2, NDC80 and CEP250 mRNA expression were all significantly associated with HCC patients’ survival." (PMID 33109182, 2020). "Further clinical validation of the tumor promoter and worse prognosis predictor function of NDC80 and MAD2L1 in local LUAD and LUSC patients as well as the genes’ relation with BUB1B and AURKA is on our way." (PMID 32795325, 2020). "Considering that NDC80 overexpression is correlated with advanced tumor stage and unfavorable prognosis, we then performed functional assays to investigate its specific biological role in CRC cells." (PMID 29341479, 2018). "In this regard, our findings are supportive of a recent review highlighting the crucial role of NDC80 in promoting tumor initiation and development." (PMID 29341479, 2018). "The results suggested NDC80 expression is correlated with tumor invasion, lymph node, and distant metastasis, implying its involvement in CRC progression." (PMID 29341479, 2018). "In this study, we compared the expression of NDC80 between tumor and adjacent normal tissues, and identified it as a potential prognostic biomarker for CRC patients." (PMID 29341479, 2018). "In summary, our results indicate that high NDC80 expression is correlated with advanced tumor stage and unfavorable prognosis in CRC patients." (PMID 29341479, 2018). "The use of single vector-expressed short-hairpin RNAs (shRNAs) has shown that the depletion of Ndc80/Hec1 significantly reduces tumour size in mice." (PMID 25557589, 2015). "Overexpression of NDC80 was found to be responsible for hyper-activating the mitotic checkpoint and inducing tumor formation." (PMID 26468983, 2015).